PRKCA (protein kinase C alpha)
Diseases named in the same sentence as PRKCA in open-access papers (continued):
Sharing a sentence is not in itself a finding about the gene and the disease.
melanoma (35 papers, 2006 to 2025). A malignant, usually aggressive tumor composed of atypical, neoplastic melanocytes. "Although mutations affecting PRKAR1A and MAPK21 are reported in some melanomas, alterations in PRKCA are uncommon in malignant melanomas." (PMID 34943205, 2021). "In addition, selected members of NFKB and NOTCH signaling pathways (IKBKB, NOTCH2, HES1, PRKCA) were strongly overrepresented in CD271+ melanoma-initiating cells." (PMID 31118427, 2019). "Protein kinase C alpha activity is elevated in some melanoma cells and is a potential target." (PMID 16969355, 2006). "In addition, PRKCA is also a key candidate gene in melanoma metastasis." (PMID 31731625, 2019). "The relative expression level of the hub genes was reverified in melanoma cell lines, and showed that HIF1A, IL1B, HMOX1, MMP3, CDKN2A and TIMP1 were upregulated, while PTEN, PRKCA, ATF3 and BRAF were downregulated in melanoma samples." (PMID 36226170, 2022). "Functional assays on a subset of these candidates, including MET, ASPM, AKAP9, IMP3, PRKCA, RPA3, and SCAP2, validated their pro-invasion activities in human melanoma cells." (PMID 20520718, 2010). "To this end, we selected 6 genes from the candidate list (ASPM, AKAP9, IMP3, PRKCA, RPA3, and SKAP2) based on literature support (see Discussion) to determine whether their knockdown would impact on the invasion of a human melanoma cell, 1205LU." (PMID 20520718, 2010).
heart failure (33 papers, 2012 to 2023). Inability of the heart to pump blood at an adequate rate to meet tissue metabolic requirements. "PRKCA as a key regulator of cardiac contractility is reported to be implicated in heart failure risks and treatment outcomes." (PMID 34482802, 2021). "As a cardiac contractile node integrator, PRKCA was suggested to profoundly affect the propensity of heart failure through intracellular Ca2+ sensing and signal transduction events." (PMID 35071383, 2021).
colon carcinoma (31 papers, 2008 to 2025). "The importance of DAGs to colon cancer has previously been discussed in the context of PLC signaling and its activation of PKC (usually PRKCA), which is associated with colon cancer." (PMID 39478120, 2024). "PRKCA was also associated with drug resistance in ovarian cancer cells, colon cancer cells, and pancreatic cancer cells." (PMID 34681275, 2021).
diabetes (28 papers, 2009 to 2025). "Variants in PRKCA are significantly associated with diabetes." (PMID 33900023, 2021). "We observed that the pro-apoptotic protein kinase C-alpha (PKCα) was specifically activated, along with enhanced superoxide production, in the developing neuroepithelium by diabetes." (PMID 28474670, 2017). "Diabetes was reported to upregulate the expression of hepatic Mdr1b (ABCB1b) mRNA and P-gp protein in 8-day diabetic Wistar rats (type 1 diabetes) induced by STZ, which was associated with the activation of protein kinase C alpha (PKCα) and nuclear factor kappa-B (NF-κB)." (PMID 32290519, 2020). "In line with previous reports, the results of our functional enrichment analysis of PTEN, PRKCA, CALR, MAP2K7 argue for their involvement mainly in the regulation of the oxidative stress response in diabetes." (PMID 39080630, 2024). "Protein kinase C alpha (PKC-α), which is a key regulator of cellular processes and a component of the JAK–STAT pathway, plays a critical role in the pathophysiology of diabetes by promoting insulin resistance, vascular dysfunction, nephropathy, and cardiovascular complications." (PMID 40333882, 2025).
lung carcinoma (26 papers, 2009 to 2025). "PRKCA has been reported to be associated with the progression of a variety of cancers, including lung cancer, chordoid gliomas and esophageal carcinoma." (PMID 33949293, 2021). "Survival analysis indicated that a high AKT2 and PRKCA expression correlated with bad prognosis in lung cancer patients." (PMID 40331978, 2025). "Network pharmacological analysis identified PIK3CG, SRC, JAK3, AKT2, and PRKCA as key potential targets of peiminine in lung cancer treatment." (PMID 40331978, 2025). "PRKCA regulates the transport activity of Rlip in lung cancer, and Rlip is an important effector of activities of PRKCA, which promote the survival, growth, and drug-resistance of cancer cells in vitro as well as phorbol ester-promoted carcinogenesis in vivo." (PMID 35158795, 2022). "In lung cancer, studies have shown that miR-328 promotes brain metastasis in non-small cell lung cancer, possibly by the upregulation of protein kinase C alpha (PRKCA)." (PMID 31900168, 2020). "Although the role of PRKCA in lung cancer has been extensively studied, results are conflicting 31-33." (PMID 32802198, 2020). "Similarly, in lung cancer, curcumin modulates the circ-PRKCA/miR-384/ITGB1 pathway, suppressing the malignancy of lung carcinoma." (PMID 36143462, 2022). "Additionally, the identified targets (PIK3CG, SRC, JAK3, AKT2, and PRKCA) may function as possible biomarkers for predicting lung cancer prognosis and guiding personalized therapy." (PMID 40331978, 2025). "Moreover, PRKCA has been confirmed to induce autophagy in lung cancer cell lines." (PMID 32681720, 2020). "MiR-203 has been characterized to act as a tumor suppressor microRNA in laryngeal carcinoma by targeting survivin and in lung cancer by targeting v-src avian sarcoma viral oncogene (SRC) and protein kinase C alpha (PKCα/PRKCA)." (PMID 32806571, 2020). "PKCα (protein kinase C alpha, PRKCA) is an important protein involved in several steps of signaling pathways in lung cancer, and microRNAs (miRNAs) have also been shown to participate in lung carcinogenesis." (PMID 24040137, 2013). "Therefore, the different mechanisms of hsa_circ_0007580 and circPRKCI in lung cancer may due to different functions of E2F7 and PRKCA." (PMID 32681720, 2020).
cardiac hypertrophy (23 papers, 2011 to 2023). "PRKCA is involved in the regulation of critical pulmonary and cardiovascular processes including angiogenesis, vascular endothelial barrier function, platelet function, arterial blood flow, cardiac hypertrophy, and endothelial cell migration and adhesion." (PMID 34538263, 2021). "PRKCA gene and protein expression was found upregulated in cardiac hypertrophy." (PMID 29868113, 2018). "PRKCA belongs to the protein kinase C (PKC) family, which is involved in regulation of cell proliferation, apoptosis, differentiation, migration, cardiac hypertrophy, and inflammation." (PMID 37762538, 2023).
prostate carcinoma (23 papers, 2010 to 2025). A carcinoma that arises from epithelial cells of the prostate gland. "A significant positive correlation between PRKCA and prostate cancer EMT signatures was observed in all cases." (PMID 36818489, 2022). "Protein kinase C, alpha (PRKCA) mediates epidermal growth factor receptor transactivation in human prostate cancer cells." (PMID 28425476, 2017). "Expression of protein kinase C alpha (PKCα) is elevated in prostate cancer (PCa); thus, we have studied whether the development of tumourigenesis in prostate epithelial cell lines modifies the normal pattern of choline (Cho) metabolite release on PKC activation." (PMID 21266973, 2011). "This analysis revealed a striking positive correlation between the expression of PKCα (PRKCA gene) and mesenchymal markers vimentin, ZEB1, ZEB2, and AXL in prostate cancer cell lines." (PMID 36818489, 2022).
glioblastoma (20 papers, 2011 to 2025). The most malignant astrocytic tumor (WHO grade IV). "In colorectal cancer, PLCE1 was slightly increased from 0.40 ± 0.03 in normal mucosa (n = 24) to 0.49 ± 0.04 in colorectal cancer (n = 45), and PRKCA was increased from 2.50 ± 0.51 in normal mucosa to 3.54 ± 1.34 in glioblastoma." (PMID 28402280, 2017). "In brain glioblastoma, PLCE1 was increased from 1.17 ± 0.06 in normal (n = 4) to 3.18 ± 1.28 in glioblastoma (n = 80), and PRKCA was increased from 1.73 ± 0.23 (n = 4) in normal to 2.11 ± 0.44 in glioblastoma (n = 80)." (PMID 28402280, 2017). "For detection of the PRKCA D463H mutation, which is characteristic for chordoid gliomas, we designed a dual probe ddPCR assay and investigated FFPE DNA extracted from three tumors histologically classified as chordoid glioma and from five glioblastoma samples." (PMID 35361262, 2022).
hepatocellular carcinoma (20 papers, 2006 to 2023). A malignant tumor that arises from hepatocytes. "MZF1 regulates the expression of the PKCα gene, PRKCA, in human hepatocellular carcinoma cells, where it binds directly to the MZF1 binding site in the PRKCA promoter region." (PMID 31963147, 2020). "In hepatocellular carcinoma, PLCE1 was significantly increased from 0.62 ± 0.15 in normal (n = 220) to 0.78 ± 0.34 in hepatocellular carcinoma (n = 225), and PRKCA was increased from 4.90 ± 1.46 in normal to 7.13 ± 4.22 in hepatocellular carcinoma." (PMID 28402280, 2017). "Previous studies have shown that TPA activates protein kinase C alpha and induces growth arrest of human hepatoma HepG2 cells." (PMID 20444294, 2010). "U3 small nucleolar ribonucleoprotein (IMP3) and protein kinase C alpha (PRKCA) had been previously linked to aggressiveness and metastasis in a variety of tumor types, including breast, colon, renal cell, lung, ovarian, and hepatocellular cancer." (PMID 20520718, 2010). "In this study, the molecular mechanism of protein kinase C alpha (PKCα) gene regulation in hepatocellular carcinoma (HCC) involving Ets-like protein-1 (Elk-1) and myeloid zinc finger-1 (MZF-1) was investigated." (PMID 26010542, 2015). "In hepatocellular carcinoma, MZF1 enhances the transcription of protein kinase C alpha (PKCα), thus facilitating the migration and invasion of cancer cells." (PMID 32042322, 2020).
pancreatic cancer (18 papers, 2010 to 2024). "One study reported that rs11079651 in PRKCA was associated with pancreatic cancer risk." (PMID 33540941, 2021).
gastric cancer (15 papers, 2012 to 2025). A primary or metastatic malignant neoplasm involving the stomach. "They discovered that 18βGA suppresses invasion and metastasis in gastric cancer cells (SGC-7901 cells) through the ROS/protein kinase C-alpha (PKCα)/ERK signaling pathway, suggesting that it could be used as a chemopreventive drug to prevent gastric cancer metastases." (PMID 36903944, 2023).
triple-negative breast carcinoma (14 papers, 2012 to 2025). An invasive breast carcinoma which is negative for expression of estrogen receptor (ER), progesterone receptor (PR), and human epidermal growth factor receptor 2 (HER2). "Recently, the MZF1/Elk-1 complex has been identified as mediator of protein kinase C alpha (PKCα) expression in triple-negative breast cancer, which induces cell migration and invasion of triple negative breast cancer cells and poor outcome." (PMID 28435519, 2017). "Recent reports demonstrate that the expression of protein kinase C alpha (PKCα) in triple-negative breast cancer (TNBC) correlates with decreased survival outcomes." (PMID 27542222, 2016). "In addition, expression of PRKCA is elevated in triple negative breast cancer (TNBC) patients and shown to be responsible for chemotherapy resistance and metastasis." (PMID 38081857, 2023).
non-small cell lung carcinoma (13 papers, 2010 to 2025). A group of at least three distinct histological types of lung cancer, including non-small cell squamous cell carcinoma, adenocarcinoma, and large cell carcinoma. "There is a study that indicated that curcumin targets the expression of ITGB1 by downregulating circ-203 PRKCA and adsorbing miR-384, thereby inhibiting the occurrence and development of non-small cell lung cancer (NSCLC)." (PMID 36291546, 2022). "Taken together, these data suggest an emerging critical role for protein kinase C alpha and beta in the tumorigenesis of non-small cell lung cancer." (PMID 25204415, 2014). "This investigation aims to prepare and optimize DOTAP cationic liposomes containing an antisense oligonuclotide (AsODN) against protein kinase C alpha in non-small cells lung cancer (NSCLC)." (PMID 24250666, 2013). "In non-small cell lung cancer (NSCLC), miR-328 has been involved in regulating cell migration and the occurrence of brain metastases by influencing the expression of the PRKCA genes." (PMID 38577014, 2024). "MiRNA-328 in non-small cell lung cancer (NSCLC) regulated cell migration and the formation of brain metastases through altered expression of the PRKCA genes." (PMID 24921708, 2014). "In addition, in Non-small cell lung cancer, FZKA also act on PRKCA and CDKN1A (p21)." (PMID 30400936, 2018).
ovarian carcinoma (13 papers, 2008 to 2025). A malignant neoplasm originating from the surface ovarian epithelium. "The function and relationships between ovarian cancer and other upregulated mRNA genes (PRKCA, HNF1A, and MAP2K5) are not clear and further investigation is necessary." (PMID 39592485, 2025).
Sepsis (13 papers, 2005 to 2026). Sepsis is defined as life-threatening organ dysfunction caused by a dysregulated host response to infection. "PRKCA has also been shown to be associated with numerous other infections, including infections by Staphylococcus aureus; with progression of sepsis and toxoplasmosis; with Burkholderia cenocepacia infections in cystic fibrosis patients; and with hepatitis E virus replication." (PMID 32019797, 2020). "PRKCA promotes mitochondrial autophagy via the miR-15a-5p/PDK4 axis to alleviate sepsis-induced ALI." (PMID 39667201, 2024). "For instance, protein kinase C-alpha (PKCα) has been identified as a key mediator of liver injury, and targeting it with inhibitors has been shown to prolong survival and restore liver function in preclinical sepsis models." (PMID 41439929, 2025).
neuroblastoma (12 papers, 2008 to 2026). Neuroblastoma (NB) is the most common solid, extracranial childhood tumor. "Indeed, the PRKC-alpha (PRKCA) is activated in brain tissues and was found in human neuroblastoma cells." (PMID 30913280, 2019). "Other studies have targeted xCT using salazosulfapyridine and protein kinase C alpha (PKCα) inhibitors to reduce intracellular GSH levels and promote ferroptosis in neuroblastoma stem cells." (PMID 37736551, 2023).
Obesity (11 papers, 2012 to 2025). Accumulation of substantial excess body fat. "At the crossroad of these events, able to further the molecular pathophysiology of obesity, we found consistent variations affecting the appearance of nuclear protein kinase C alpha (PKCα) in adipocyte cultures in which PKP2 levels were modulated." (PMID 37607954, 2023). "The potential pleiotropic effect of PRKCA gene on asthma and BMI was demonstrated by different SNPs influence on asthma or obesity, including rs9892651." (PMID 27411394, 2016). "Specifically, some of the most known candidate genes and genetic loci for asthma and allergy have already been linked to the pathogenesis of obesity such as the tumor necrosis factor alpha (TNF-a) gene, the protein kinase C alpha (PRKCA) gene and β2‐adrenergic receptor (ADRB2)." (PMID 27411394, 2016). "A common point has been the link of PCa biomarkers, obesity-related factors, as well as KAT5, PRKCA, and SUMO1 to NF-kB, a transcription factor, involved in proliferation, inflammation, and apoptosis, all tumor-promoting processes." (PMID 40481981, 2025).
endometrial cancer (10 papers, 2010 to 2025). Primary or metastatic malignant neoplasm involving the endometrium (mucous membrane that lines the endometrial cavity). "In the case of NES, slight differences were noted in G2 endometrial cancer, and for PRKCA in G1 and G3 samples." (PMID 31795319, 2019).
Insulin resistance (10 papers, 2010 to 2025). Increased resistance towards insulin, that is, diminished effectiveness of insulin in reducing blood glucose levels. "Activation of PRKCA mediates serine/threonine phosphorylation of the insulin receptor resulting in decreased active form of insulin receptor, inducing insulin resistance." (PMID 21689475, 2011). "Transcriptomic data show that insulin secretion‐related genes (IRS1, PRKCA/PKCα) in cave loaches are significantly downregulated, rather than exhibiting mutations related to insulin resistance." (PMID 41383212, 2025).
leukemia (10 papers, 2016 to 2023). A malignant (clonal) hematologic disorder, involving hematopoietic stem cells and characterized by the presence of primitive or atypical myeloid or lymphoid cells in the bone marrow and the blood. "High PRKCA levels in leukemia cells protect the cells from apoptosis via BCL2 activation." (PMID 33488754, 2020). "The upregulation of PRKCA has shown to have implications in OSCC, and attributed to chemoresistance by the phosphorylation of BCL2 in leukemia." (PMID 36703917, 2022).
type 2 diabetes (9 papers, 2010 to 2024). "Two targets, PRKCA and RHOA proteins, and four signaling pathways, including the mTOR signaling pathway, Type II diabetes mellitus, and Ras and Rap1 signaling pathway, were predicted and considered as key nodes and pathways through which Forsythiaside ameliorated DKD podocytopathy." (PMID 36712665, 2022).
Alzheimer disease (8 papers, 2021 to 2025). A progressive, neurodegenerative disease characterized by loss of function and death of nerve cells in several areas of the brain leading to loss of cognitive function such as memory and language. "Microglia express GPNMB in the brains of Alzheimer's disease and Nasu-Hakola disease, PRKCA is associated with neural basis of episodic remembering in healthy individuals and KCNMB4 is downregulated in hippocampal granule neurons following seizure activity." (PMID 38632500, 2024). "Protein kinase C alpha (PKCα) is necessary for producing synaptic loss by Aβ, which leads to learning and memory deficits by contributing to human late-onset Alzheimer’s disease." (PMID 36012331, 2022). "Mutations that enhance the activity of protein kinase C alpha (PKCα) are associated with Alzheimer’s Disease." (PMID 36418293, 2022). "In the pathway unification database, SRC, EGFR, MAPT, APP and PRKCA were identified as key molecules in the pathway of Alzheimer’s disease." (PMID 37010714, 2023).
asthma (8 papers, 2013 to 2024). "PRKCA is associated with both BMI and asthma simultaneously, along with other genes with pleiotropic effects like leptin (LEP), and tumor necrosis factor (TNF)." (PMID 33791298, 2021). "Overall, all these data suggest that any or all of these genes—PLA2G4A, PLA2R1, RELA, PRKD1, and PRKCA—may play a role in the risk of asthma in adults in association with exposure to LMW agents or irritants." (PMID 27504716, 2017). "Studies have found that the protein kinase C alpha (PRKCA) gene, leptin gene (LEP), and β3-adrenergic receptor gene (ADRB3) are associated with asthma and BMI." (PMID 38292857, 2023). "This study identified interactions between genetic variants near or within five genes, PLA2G4A, PLA2R1, RELA, PRKD1 and PRKCA, and occupational exposures to LMW agents or irritants for current adult-onset asthma." (PMID 27504716, 2017).
lung adenocarcinoma (8 papers, 2014 to 2024). A carcinoma that arises from the lung and is characterized by the presence of malignant glandular epithelial cells. "PRKCA overexpression has been associated with reduced survival outcomes not only in ACC patients but also in lung adenocarcinoma." (PMID 37895143, 2023). "Additionally, PRKCA expression was elevated in lung adenocarcinoma and positively associated with T classification, N classification, lymph node metastasis." (PMID 34299042, 2021). "However, upregulation of PRKCA may be an unfavorable factor that leads to lung adenocarcinoma." (PMID 39689118, 2024). "Among them, the up-regulation of PRKCA and HDGF is considered to be a negative factor for the development of lung adenocarcinoma." (PMID 36339610, 2022).